NANOG (Nanog homeobox)
Diseases named in the same sentence as NANOG in open-access papers (continued):
Sharing a sentence is not in itself a finding about the gene and the disease.
prostate carcinoma (continued). "We and others have identified other members of the pluripotent stem cell transcriptional circuitry as being important AR-regulated oncogenes in prostate cancer, including SOX2 and NANOG; however, we rarely see these co-expressed in cancer, or in particular, expressed with OCT4." (PMID 39858088, 2025). "In prostate cancer, MUC1-C has been shown to activate the BAF complex in prostate cancer stem cells, enhancing the expression of NOTCH1 and NANOG, thus promoting self-renewal of tumor stem cells and accelerating the progression of neuroendocrine prostate cancer." (PMID 38361923, 2024). "Mutation in the tumor suppressor SPOP and negative regulator of NANOG also leads to increased stemness of prostate cancer and a negative prognosis in prostate cancer." (PMID 35205716, 2022). "Additionally, in a 2015 report, CRISPR-Cas9-mediated gene knockout of NANOG and NANOGP8 was observed to decrease the malignant potential of prostate cancer cells." (PMID 32765953, 2020). "Our experiments establish MDA-9 as a critical regulator of stem cell phenotypes in prostate cancer that are responsible for PCSC maintenance and survival through regulation of multiple stem-regulating molecules such as NOTCH1, C-myc, STAT3, NANOG, OCT4 and SOX2." (PMID 31878027, 2019). "It is not surprising that prostate cancers highly expressing pluripotential transcription factors, such as NANOG, OCT4, and SOX2, more rapidly develop castration resistance and are associated with a poor outcome." (PMID 31366128, 2019). "CD44+CD133+ and CD133+ cells are markers of prostate CSCs in human prostate cancer tissues, and these immune cells express higher NANOG mRNA levels compared to their corresponding negative cells." (PMID 26087476, 2015). "Neither retinoic acid nor cisplatin induced resistance in cervical or prostate cancer cell lines or other germ cell tumor lines in which they failed to alter the expression of NANOG and POU5F1." (PMID 24475288, 2014). "Studies of the roles of SPOP and PIN1 in prostate cancer stemness and progression have revealed that PIN1 is an upstream regulator of NANOG and also protects the latter from SPOP-mediated polyubiquitination and degradation, thus promoting NANOG-conferred cancer stemness features in prostate tumors." (PMID 32268506, 2020). "All prostate cancers were histopathologically identified as adenocarcinomas of various grades, and cancer cells and intraepithelial neoplasia (high grade) were immunohistochemically shown to express NANOG and OCT4, but not CD133 and NESTIN." (PMID 25120646, 2014). "We postulate that the transition of prostate cancer from adenocarcinoma to non-adenocarcinoma and small cell carcinoma involves activation of scTF genes in the sequence of POU5F1 → LIN28A/SOX2 → NANOG with tumor cells adopting a more de-differentiated state." (PMID 31146720, 2019). "The immunoreactivities of NANOG (P<0.001) and OCT4 (P<0.01) in prostate cancer was significantly greater than those in the non-cancerous cells." (PMID 25120646, 2014). "Like 5D3 and SP cells, the different non-luminal-like prostate cancer cell types showed little expression of LIN28, POU5F1, NANOG, SOX2." (PMID 21605402, 2011).
glioma (48 papers, 2011 to 2025). A benign or malignant brain and spinal cord tumor that arises from glial cells (astrocytes, oligodendrocytes, ependymal cells). "The present study aimed to quantify the expression profiling of longevity-related transcriptional factors SOX2, OCT3/4, and NANOG to evaluate their diagnostic and performance values in high-grade gliomas." (PMID 29849920, 2018). "An association between higher NANOG expression and aggressive grades of gliomas was also demonstrated." (PMID 23483195, 2013). "Hitherto, it is unknown about the role of exosomal hsa_circ_0072083 (circ_0072083) in TMZ resistance in glioma, and whether it is associated with NANOG via regulating miRNA sponge and methylation." (PMID 33975615, 2021). "Furthermore, recently its role as glioma stem cell biomarker has been described in association with NANOG and OCT." (PMID 34012924, 2021). "Consistent with NS-culture-derived glioma cells with high invasiveness, genes highly expressed in 51A were those encoding markers of neural stem/precursor cells (NANOG, POU3F2, POU5F1, and SALL2), and pro-invasive proteins (AGAP2, EPHA2, FOXM1, PDGFRA, and TNC)." (PMID 29113349, 2017). "Thus, further investigation is warranted to characterize the expression of SOX2, OCT4, and NANOG in grade IV gliomas and examine potential associations with patient outcome and tumor aggressiveness." (PMID 26258069, 2015). "qPCR analysis of 38 genes was investigated, including the glioma cell marker, GFAP; prognostic glioma classification markers, IDH1/2; and glioma cell stemness markers, NANOG, SOX2, SOX2-OT and CD133." (PMID 41034696, 2025). "TGF-β is secreted by gliomas, and its expression increases under hypoxia due to the activity of NANOG, a transcription factor induced by HIF-1α, which promotes the stemness signature of GSCs." (PMID 38794149, 2024). "Other studies also show the high expression of NANOG in tumor samples more than in normal tissue like oral squamous cell carcinoma, salivary glands (mucoepidermoid), and glioma." (PMID 35186145, 2022). "In short, circ_0072083 depletion inhibited ALKBH5 expression via releasing miR-1252-5p, which further downregulated NANOG expression, thus alleviating temozolomide resistance by inhibiting the maintenance of glioma stem cells." (PMID 35843942, 2022). "When circ-0072083 is downregulated, the demethylation of ALKBH5 is eliminated, and the expression level of NANOG is downregulated, thus achieving the regulation of drug resistance in glioma." (PMID 35688823, 2022). "For example, the abnormal expression of PVT1 affects the expression of NANOG and thus makes difference in the development of glioma." (PMID 35127729, 2021). "Previous studies suggested that NANOG contributed to the glioma malignancy via promoting cell growth." (PMID 33975615, 2021). "For example, exosomal circ_0072083 was reported to contribute to TMZ resistance in glioma via modulating exosomal miR-1252-5p-mediated nanog homeobox (NANOG) degradation." (PMID 35095909, 2021). "Exosomal circ_0072083 promoted TMZ resistance via increasing NANOG via regulating miR-1252-5p-mediated degradation and demethylation in glioma." (PMID 33975615, 2021). "In this study, we mainly investigated the promoting effect of exosomal circ_0072083 on TMZ resistance, and validated the regulatory network of circ_0072083/miR-1252-5p/NANOG in glioma." (PMID 33975615, 2021). "Recently, it was also shown that the induction of the Ten-eleven Translocation (TET) family of DNA demethylases by hypoxia promotes the expression of the stem cell genes OCT4 and NANOG in glioma cells." (PMID 33391498, 2021). "Gene expression of glioma samples revealed enrichment of a stemness signature that included the stemness markers NANOG, OCT4, SOX2, and BMI1 that correlated with tumor grade." (PMID 32957513, 2020).
glioma (continued). "We and others have shown previously that sphere cultures expanded from glioma LN18 cells in serum-free medium with growth factors are characterized by the higher expression of pluripotency markers (NANOG, POU5F1, SOX2, CD133)." (PMID 30654849, 2019). "We have previously implemented a protocol to cultivate LN18 sphere cultures enriched in glioma CSCs which expressed higher levels of the pluripotency markers: NANOG, POU5F1, SOX2, and CD133 as compared to the parental/adherent tumor cells." (PMID 30654849, 2019). "NANOG, a stem cell marker, was expressed in glioma cells in the peri-necrotic area, both Ki-67-positive and negative cells, while its expression was diminished in glioma cells in the non-necrotic area." (PMID 30465075, 2019). "NANOG is known to be a key molecule in regulating glioma stem cells and is located downstream of the hedgehog signaling pathway." (PMID 28245563, 2017). "Grade III and IV glioma tissues presented strong expression and localization of NANOG in the nuclei of glioma cells, whereas lower grade gliomas displayed low to moderate expression of this gene." (PMID 26258069, 2015). "The amplified expression levels of SOX2, OCT4, and NANOG transcription factors in grade IV gliomas implicate a possible clinical intervention." (PMID 26258069, 2015). "Current research demonstrates a positive correlation between the expression of SOX2, OCT4, and NANOG and the pathological grade of gliomas." (PMID 26258069, 2015). "For example, our previous study indicated that the ESC transcriptional factor, NANOG, was overexpression in glioma tissues when compared with that in normal brain tissues at the mRNA and protein levels." (PMID 23483195, 2013). "This increase in NANOG expression also results in increased TMZ resistance in gliomas." (PMID 40469294, 2025). "Additionally, miR-1252-5p also serves as an inhibitor of ALKBH5, suppressing ALKBH5-mediated demethylation and thereby reducing NANOG expression in gliomas." (PMID 40469294, 2025). "More importantly, multiple evidences have confirmed that NANOG could facilitate TMZ resistance in glioma." (PMID 33975615, 2021). "In conclusion, exosomal circ_0072083 could promote TMZ resistance in glioma by increasing NANOG, possibly via regulating miR-1252-5p-mediated degradation and miR-1252-5p/ALKBH5 axis-mediated demethylation." (PMID 33975615, 2021). "Our study was the first time to validate miR-1252-5p could interact with circ_0072083 and NANOG, thus resulting in that circ_0072083 could modulate NANOG indirectly via miR-1252-5p to regulate TMZ resistance in glioma." (PMID 33975615, 2021). "Similarly, while stimulation of glioma cells with soluble DLK1 boosted the increase in the expression of the stem cell marker genes NANOG, OCT4, and SOX2 in hypoxic cells, addition of PT2385 blocked this specific DLK1 effect in all cell lines tested." (PMID 33142235, 2020). "Interestingly, immunohistochemical analyses of human brain tumour samples further confirmed NANOG expression in grade IV gliomas." (PMID 26899176, 2016). "NANOG, SOX2 and POU5F1, three stemness-associated genes that are part of the FA-BSA-NP delivery system, could facilitate autophagy inhibition and chemotherapy efficacy in glioma therapy." (PMID 34475426, 2021). "Hence, we thought miR-1252-5p could directly target NANOG 3’UTR or inhibit ALKBH5-mediated demethylation to reduce NANOG expression in glioma." (PMID 33975615, 2021). "Additionally, NANOG might be activated via the aberrant Notch signaling to promote tumor recurrence and invasion in glioma." (PMID 33975615, 2021). "The expression of various glioma stemness markers – NANOG (4-fold increase), SOX2 (3-fold increase), SOX2-OT (15-fold increase) and CD133 (3-fold increase) – were also significantly increased in high-grade glioma samples compared to the controls." (PMID 41034696, 2025).
glioma (continued). "FERMT1 knockdown significantly suppressed of MYC, OCT4 and NANOG expression in U-251 MG and T98G cells, which coordinately supported the regulatory role of FERMT1 in self-renewal and stem cell-like properties in glioma." (PMID 38976072, 2024). "As expected, GSCAR expression positively correlated with glioma stem cell biomarkers, including CD133, CD44, NANOG, ALDH1, Oct4, SOX2, and c-Myc." (PMID 37063420, 2023). "In glioma, TFAP2A disturbs the expression of stemness-related genes, such as NANOG, SOX2 and CD133, via both directly binding the regulation region of NANOG and indirectly interfering with the IL6/JAK2/STAT3 signaling pathway." (PMID 37291585, 2023). "NANOG is also transcribed by GLI1 activation, and they both constitute an axis that promotes stemness and growth in gliomas." (PMID 34638956, 2021). "Stem cell transcription factors (SOX2, OCT4, and NANOG) and ABCA1 are responsive to regulation by CEBPD, which directly binds to the promoter regions of those genes in glioma spheroid cells and TMZ-treated glioma cells." (PMID 33436575, 2021). "In this research, we aimed to study the function of exosomal circ_0072083 on TMZ resistance, and explore the regulatory network of circ_0072083/miR-1252-5p/ NANOG via competitive sponge and ALKBH5-mediated demethylation pathways in glioma." (PMID 33975615, 2021). "Similarly, we also found that ALKBH5 could increase NANOG expression in glioma." (PMID 33975615, 2021). "Among these pluripotent transcription factors overexpressed in high-grade gliomas are “sex-determining region Y-Box (SOX2), octamer-binding transcription factor 4 (OCT 4), and Nanog homeobox (NANOG)”." (PMID 29849920, 2018). "We expanded GSCs from glioma LN18 cells in serum-free medium with growth factors and confirmed the higher expression of pluripotency markers (NANOG, SOX2, CD133) in GSCs-enriched spheres, as previously shown." (PMID 30450051, 2018). "Western blotting analysis showed that nestin, NANOG, and SSEA-1 were present in the CD133+ cells derived from C6 glioma cells." (PMID 29284440, 2017). "The authors showed time-dependent decrease of OCT3/4, NANOG and SOX2 expression in glioma spheres after SPP1 knockdown." (PMID 28030801, 2017). "CD133+ C6 glioma cells were treated with STAT3 inhibitors WP1066 (5 μM) or S3 l-201 (50 μM) for 24 h and p-STAT3, STAT3, CD133, Nestin, SSES-1, and NANOG were measured using Western blotting analysis." (PMID 29284440, 2017). "Treatment with SI113, alone or in combination with EPO-A or VCR, yielded a modification of mRNA expression for OCT3/4, NANOG, NESTIN and OLIG2, all GBM or glioma stemness markers." (PMID 29340013, 2017). "The levels of NANOG and OCT3/4 mRNA were significantly higher in sorted Rhod123(–) cells than in the bulk cells in all tested glioma cultures." (PMID 28030801, 2017). "In murine PDGFB-induced glioma cultures and primary human GBM cultures stroma-derived osteopontin was responsible for up-regulation of NANOG, SOX2, OCT4, and ID1 expression." (PMID 28030801, 2017). "Human gliomas have shown expression of SOX2, OCT4 and NANOG, postulating the CSC theory and mutagenic transformation from normal NSCs." (PMID 26580604, 2015). "Western blot results, mRNA levels and immunohistochemical data of several human glioma specimens demonstrated greater expression of SOX2, OCT4 and NANOG in higher-grade gliomas than lower grade tumours." (PMID 26580604, 2015). "NANOG-positive cells also express CD133, a well-established CSC marker, and the expression level of CD133 is reported to correlate with the pathological grade of the glioma." (PMID 37372456, 2023). "The HH-GLI signaling was also shown to activate stemness-related transcription factors, such as NANOG, OCT4, SOX2, and BMI1 in gliomas, while its inhibition reduces NANOG expression, decreases cell proliferation and colony formation, and abolishes cisplatin resistance in OC cells." (PMID 37445860, 2023).
glioma (continued). "Additionally, in silico differential analysis of PROM1, SOX2, and NANOG transcript levels was performed on clinical samples from GBM and low-grade glioma (LGG) and compared to healthy tissues as described in the Methods section." (PMID 36497426, 2022). "In addition, circ-0072083 can also target miR-1252-5p to affect the expression of NANOG and ALKBH5 and regulate the drug resistance of glioma." (PMID 35688823, 2022). "Indeed, its endogenous expression is inversely correlated with NANOG and OCT4, and its ectopic expression in glioma stem cells is sufficient to repress OCT4 and NANOG, as well as tumor aggressiveness." (PMID 34439740, 2021). "NANOG contributes to tumor cell growth and TMZ resistance in glioma." (PMID 33975615, 2021). "Prasad and colleagues demonstrated that hypoxic environment could induce the demethylation in glioma cells by overexpression of TET1 and TET3, then promoted the stemness of tumor cells by upregulating OCT4 and NANOG expression." (PMID 32014008, 2020). "LN18 glioma cells grown as non-adherent cells at a low density under serum-free conditions form spheres and display higher expression of stemness markers (NANOG, POU5F1, SOX2 and PROM-1) than adherent LN18 cells." (PMID 33050631, 2020). "The proliferation of CD133+ CSCs isolated from CSCs derived from the U251 and SF295 glioma cell lines and from human glioma samples was upregulated on a time- and concentration-dependent basis by LPS stimulation, with increases in CD133, NANOG, and NESTIN mRNA and protein levels." (PMID 28881826, 2017). "In addition, the survival rate of glioma cells and the expression of cancer stem cell markers Nestin, SSES-1, and NANOG were attenuated by WP1066." (PMID 29284440, 2017). "In addition, in vitro studies of glioma cell lines in conditions that promote stemness and tumoursphere formation increased expression of SOX2, OCT4 and NANOG." (PMID 26580604, 2015). "Nanog homeobox is another transcription factor playing a crucial role in the self-renewal and differentiation of ESCs; therefore, it is no surprise that NANOG expression has been detected in human gliomas." (PMID 26258069, 2015). "In brain tumors, this subset of cells, known glioma stem cells (GSCs), exhibit self-renewal that can be measured in vitro via neurosphere formation assays and the expression of molecular markers (e.g. SOX2, NANOG, CD15, CD133) in symmetric and asymmetric division studies." (PMID 33391498, 2021). "First, primary and lined glioma cells were infected with or without ADV, and the expression of pluripotency factors c-MYC, SOX2, OCT4 and NANOG were determined by RT-qPCR and western blotting." (PMID 32843056, 2020).